BIRC5 (baculoviral IAP repeat containing 5)
Diseases named in the same sentence as BIRC5 in open-access papers (continued):
Sharing a sentence is not in itself a finding about the gene and the disease.
ovarian carcinoma (continued). "To understand how BIRC5 regulates EMT in ovarian cancer cells, we tested the correlation between survivin and the TGFβ pathway in ovarian cancer cells." (PMID 29212257, 2017). "BIRC5 expression significantly correlated with overall poor survival in patients based on analyzing data from 514 ovarian carcinomas." (PMID 29212257, 2017). "Lentiviral CRISPR/Cas9 nickase vector mediated BIRC5 editing led to the inhibition of EMT in ovarian cancer SKOV3 and OVCAR3 cells." (PMID 29212257, 2017). "Our data indicate that disruption of BIRC5 expression enhanced the efficacy of chemotherapy in ovarian cancer cells." (PMID 29212257, 2017). "Our data indicated that loss of BIRC5 expression attenuated the TGFβ signaling pathway, thereby potentially leading to the inhibition of EMT in ovarian cancer cells." (PMID 29212257, 2017). "In this study, we demonstrated for the first time that BIRC5 expression promoted EMT in ovarian cancer cells, which is consistent with a previous study reported in colorectal cancer." (PMID 29212257, 2017). "Collectively, our studies demonstrated that disruption of BIRC5 expression inhibited EMT by attenuating the TGFβ pathway in ovarian cancer cells." (PMID 29212257, 2017). "To examine the expression level of BIRC5 in ovarian cancer, we analyzed TCGA datasets that included 586 serous ovarian carcinomas and 8 normal ovary controls." (PMID 29212257, 2017). "To disrupt BIRC5 expression in ovarian cancer cells, we examined endogenous BIRC5 expression in several ovarian cancer cell lines including SKOV3, OVCAR3, Hey and UACC1598 by western blot." (PMID 29212257, 2017). "To determine whether the transcription of the BIRC5 gene was actually required for the survival of the ovarian cancer cells, we treated them with YM155, a pharmacological inhibitor of survivin expression that blocks the promoter activity of the BIRC5 gene." (PMID 37445993, 2023). "In ovarian cancer, the cells’ ability to proliferate, migrate, and invade other tissues can be slowed down through both molecular suppressions by gene editing techniques and drug inhibition by BIRC5 antagonists." (PMID 36358602, 2022). "In ovarian cancer, the cells’ ability to proliferate, migrate, and invade other tissues can be slowed down through both molecular suppressions by gene editing approaches and pharmacological inhibition by BIRC5 antagonists." (PMID 36358602, 2022). "The expression of BIRC5 proteins correlates with poor differentiation and worse disease prognosis of malignant peripheral nerve sheath tumors, renal cell carcinoma, lung adenocarcinoma and ovarian cancer 61-64." (PMID 33995639, 2021). "Recently, we have shown that BIRC5 expression promoted EMT in ovarian cancer cells." (PMID 30241553, 2018). "Overexpression of miR-203 inhibits EMT by targeting BIRC5 in ovarian cancer SKOV3 and OVCAR3 cells." (PMID 30241553, 2018). "To examine whether BIRC5 is a target gene of miR-203 in ovarian cancer cells, we established miR-203-expressing SKOV3 and OVCAR3 stable cell lines using lentiviral vector." (PMID 30241553, 2018). "In this study, we tested our hypothesis that miR-203 inhibits ovarian tumor metastasis by suppressing EMT through targeting BIRC5, using an orthotopic ovarian cancer mouse model." (PMID 30241553, 2018). "For the first time, we found that BIRC5 expression was required for activating the TGFβ pathway and inhibiting survivin by using molecular or pharmacological approaches led to attenuating TGFβ signaling in ovarian cancer cells." (PMID 29212257, 2017). "In addition, inhibition of survivin sensitized cell responses to chemotherapy drug treatment, indicating that BIRC5 is a therapeutic target for ovarian cancer therapy." (PMID 29212257, 2017). "We are in the process of testing our hypothesis: inhibiting BIRC5 expression suppresses tumor metastasis in an orthotopic ovarian cancer mouse model by using selective small molecule survivin inhibitors." (PMID 29212257, 2017).
ovarian carcinoma (continued). "Although we showed that BIRC5 was highly expressed in high grade serous ovarian carcinoma, the role of BIRC5 expression in other types of ovarian cancer, including mucinous, clear cell, and endometrioid carcinoma was still unknown." (PMID 29212257, 2017). "Therefore, additional studies are required to determine the correlation of BIRC5 expression with diverse types of ovarian cancer at various disease stages in order to define its potential role in diagnosis, prognosis, and therapy." (PMID 29212257, 2017). "In addition, we examined BIRC5 expression in ovarian cancer in the Oncomine database including 43 serous carcinomas and 10 peritoneal controls; BIRC5 expression showed approximately a 20-fold increase in tumors compared to controls (P=5.68E-8)." (PMID 29212257, 2017). "Therefore, BIRC5 is a promising drug target for ovarian cancer therapy because of its role in EMT and undetectable expression in normal ovarian tissues." (PMID 29212257, 2017). "To confirm the findings of BIRC5 expression in ovarian cancer, we performed immunofluorescent staining on tumor sections of high grade serous ovarian carcinoma and found strong immunoreactivity for survivin in tumor cell nuclei but absent in the adjacent normal tissues." (PMID 29212257, 2017). "Although no studies have so far reported on survivin and tumor metastasis in orthotopic ovarian cancer animal models, several studies have shown that silencing BIRC5 expression with siRNA, shRNA, or YM155 inhibited cell proliferation and sensitized the cell response to chemotherapy." (PMID 29212257, 2017). "Furthermore, EA decreased the ability of ovarian cancer cells for migration, increased the rate of apoptosis by inhibiting BIRC5 and activating CASP3, triggered cell cycle arrest in the G2/M phase, and caused a decrease in mitochondrial membrane potential and genotoxic effects." (PMID 40405479, 2025). "Numerous researches have shown that BIRC5 contributes to tumor cell immune escape by inhibiting apoptosis and confirmed that its expression is strongly correlated with prognostic status and OS in various cancers (e.g., lung, colorectal, prostate, and ovarian cancers)." (PMID 34988121, 2021). "BIRC5 expression in ovarian cancer cells may contribute to chemoresistance." (PMID 29212257, 2017). "Thus, targeting BIRC5 by using small molecule inhibitors like YM155 may provide a novel therapeutic approach in ovarian cancer therapy by inhibiting ovarian tumor metastasis and overcoming chemoresistance." (PMID 29212257, 2017). "Blocking BIRC5 expression by using YM155 inhibitor effectively reduced the migration and invasion rates of ovarian cancer cells, EMT, migration and invasion were also inhibited." (PMID 35461228, 2022). "FOXM1, as a transcription factor, regulated many important proliferation-related target genes (AURB, CCNB1, BIRC5, CDC25, and PLK1, etc.)and was important oncogenic driver in ovarian cancer progression." (PMID 34966670, 2021). "It has been reported that overexpression of β-hCG (CGB5 gene) in the ovarian cancer cell lines OVCAR-3 and SKOV-3 showed a remarkable decrease in the expression of BCL2, but increased expression of BAX and BIRC5." (PMID 34941061, 2021). "The ovarian cancer cell lines showed increased BIRC4 and BIRC5 expression in A2780/4OHP and A2780/cOHP, respectively." (PMID 31344863, 2019). "We previously reported that miR-203 functions as a tumor suppressor in ovarian cancer cells by directly targeting transcription factor Snai2 and inhibiting epithelial to mesenchymal transition (EMT), whereas BIRC5/survivin promotes EMT." (PMID 30241553, 2018). "Inhibition of BIRC5 expression by using a small molecule inhibitor of survivin, YM155, also suppressed EMT in both ovarian cancer cell lines." (PMID 29212257, 2017). "Our results in ovarian cancer agree with previouslypublished reports of high expression of EPCAM localised to the membrane and highexpression of BIRC5 evenly distributed between the cytoplasm and nucleus." (PMID 21423607, 2011).
ovarian carcinoma (continued). "Overexpression of ZBTB10 in human ovarian cancer cell lines led to suppression of FSH-induced angiogenesis by downregulating VEGF, COX2 and survivin [baculoviral inhibitor of apoptosis repeat-containing 5 (BIRC5)]." (PMID 39385609, 2024). "BIRC5 expression promoted EMT, whereas knockout of BIRC5 inhibits EMT in ovarian cancer cells." (PMID 30241553, 2018). "Strategies for inhibiting BIRC5 are now utilized in several ongoing clinical trials on different cancer forms, but so far not in ovarian cancer." (PMID 23029477, 2012). "The overabundance of T-type Ca2+ channels in ovarian cancer leads to PI3K/AKT overexpression and, consequently, treatment with mibefradil, which is a calcium channel blocking agent, decreased nuclear FOXM1 protein levels and its binding to the BIRC5 (survivin) promoter in EOC cells." (PMID 34205406, 2021). "BIRC5 was reported to be a target gene of miR-203 in leukemia and hepatocellular carcinoma (HCC), which prompted us to hypothesize that miR-203 may regulate ovarian tumor metastasis by targeting BIRC5 in ovarian cancer cells." (PMID 30241553, 2018). "Although it is not known how BIRC5 contributes to ovarian tumor metastasis, it is interesting to note that BIRC5 expression was downregulated in ovarian cancer cells by miR-203, suggesting that the miR-203/BIRC5 axis regulates ovarian tumor metastasis by inhibiting EMT." (PMID 30241553, 2018). "We found that BIRC3 expression correlated inversely with ovarian cancer patient outcome, while BIRC2, BIRC4, BIRC5, and BIRC7 had no significant impact on patient outcome." (PMID 30718461, 2019). "To determine the functional outcome of losing BIRC5 expression in ovarian cancer cells, we examined cell proliferation in SKOV3 and OVCAR3 cells with and without BIRC5 expression." (PMID 29212257, 2017).
lung adenocarcinoma (39 papers, 2013 to 2025). A carcinoma that arises from the lung and is characterized by the presence of malignant glandular epithelial cells. "This study also highlights BIRC5’s significant overexpression in lung adenocarcinoma (LUAD) and its strong association with tumor progression." (PMID 39703228, 2024). "Survival analysis indicated that high BIRC5 expression was associated with poor prognosis across multiple cancers, including lung adenocarcinoma (LUAD) and kidney renal clear cell carcinoma (KIRC)." (PMID 39703228, 2024). "This study highlights the significant overexpression of BIRC5 in various cancers, with particularly strong associations observed in lung adenocarcinoma, where BIRC5 is closely linked with tumor progression and poor prognosis." (PMID 39703228, 2024). "A high expression level of BIRC5 has been identified in lung adenocarcinoma and was associated with high risk of distant metastasis and tumor bearing in patients." (PMID 35461228, 2022). "The recent study noted that the high-expression BIRC5 was correlated with low overall survival in lung adenocarcinoma patients, and the overexpression of BIRC5 is a risk factor for a worse prognosis." (PMID 34938346, 2021). "High BIRC5 expression is associated with tumor progression in lung adenocarcinoma and poor patient prognosis." (PMID 31626592, 2019). "Multiple research studies have indicated that a significant number of cancer types frequently exhibit elevated levels of BIRC5, which is linked to resistance against chemicals and an unfavorable prognosis in individuals with cancer, such as lung adenocarcinoma, neuroblastoma, and glioma." (PMID 37895143, 2023). "Besides, it has been revealed that the attenuation of the long non-coding RNA LINC00857 significantly augments the susceptibility of lung adenocarcinoma cells to radiotherapy, contingent upon BIRC5 expression, by inducing the recruitment of NF-κB1." (PMID 37741993, 2023). "In addition, the ratio of miR-195 level to BIRC5 level is associated with both recurrence-free and overall survival in lung adenocarcinoma." (PMID 29416000, 2018). "Functional experiments in lung adenocarcinoma (LUAD) revealed that BIRC5 upregulation enhances cell proliferation, migration, and invasion, while its knockdown suppresses these activities." (PMID 39703228, 2024). "Our findings have unraveled that BIRC5 holds promise as a novel biomarker and therapeutic target for lung adenocarcinoma." (PMID 37834111, 2023). "Flow cytometry analysis, lactate dehydrogenase release (LDH) assay and Micro-PET imaging were performed in A549 cells and a mouse xenograft tumor to explore the function of BIRC5 in cell death of lung adenocarcinoma." (PMID 37834111, 2023). "We found that BIRC5 was up-regulated and related to a high mortality rate in lung adenocarcinoma patients." (PMID 37834111, 2023). "After testing the mRNA level of BIRC5 in four different lung adenocarcinoma cell lines (BEAS-2B, A549, H1299, and H1650), we selected A549 cells for further experiments." (PMID 37741993, 2023). "The results showed that BIRC5 is a new target for the diagnosis and treatment of lung adenocarcinoma, and that its expression was significantly elevated in LUAD and more positively associated with tumor progression." (PMID 37834111, 2023). "For instance, it would be advantageous to incorporate a broader range of lung adenocarcinoma cell lines to explore the correlation between BIRC5 inhibition-induced pyroptosis and cellular GSDME expression levels." (PMID 37834111, 2023). "The obtained data indicated that miR‐126‐5p promoted radiosensitivity of lung adenocarcinoma cells via the EZH2/KLF2/BIRC5 axis while overexpressed BIRC5 reversed the action of miR‐126‐5p." (PMID 35322532, 2022). "RT‐qPCR showed that BIRC5 expression increased in lung adenocarcinoma tissues and cells, and the same result was found by the immunohistochemical staining." (PMID 35322532, 2022).
lung adenocarcinoma (continued). "Both in vitro and in vivo experiments verified that elevated miR‐126‐5p inhibited cell migration and promoted apoptosis to enhance the sensitivity of lung adenocarcinoma cells to radiotherapy via the EZH2/KLF2/BIRC5 axis." (PMID 35322532, 2022). "miR‐126‐5p and KLF2 were poorly expressed, while EZH2 and BIRC5 were upregulated in lung adenocarcinoma tissues and cells." (PMID 35322532, 2022). "We then study the effect of miR‐126‐5p regulating the EZH2/KLF2/BIRC5 axis on the radiosensitivity of lung adenocarcinoma cells." (PMID 35322532, 2022). "Due to the limited known researches, the roles of miR‐126‐5p, EZH2, KLF2, BIRC5 as well as their interaction in the radio‐resistance of lung adenocarcinoma cells should be more clearly investigated." (PMID 35322532, 2022). "Collectively, miR‐126‐5p downregulated EZH2 to facilitate the sensitivity of lung adenocarcinoma cells to radiotherapy via KLF2/BIRC5." (PMID 35322532, 2022). "The objective of our study was to investigate the effect of miR‐126‐5p, EZH2, KLF2 and BIRC5 in radio‐resistance of lung adenocarcinoma cells and their inner mechanisms." (PMID 35322532, 2022). "Silencing of BIRC5 inhibited cell proliferation and colony formation but enhanced apoptosis and radiosensitivity of lung adenocarcinoma cells." (PMID 35322532, 2022). "Consistently, RT-qPCR and Western blotting results in our study revealed that BIRC5 was highly-expressed in lung adenocarcinoma." (PMID 34372869, 2021). "On the other hand, Baculoviral IAP repeat containing 5 (BIRC5) is up-regulated in lung adenocarcinoma cells and tissues, wherein radiosensitivity was found to influence the dependance on BIRC5 expression." (PMID 34372869, 2021). "Subsequent experimentation in our study revealed that NPs exerted a suppressive effect on BIRC5 expression in lung adenocarcinoma cells." (PMID 34372869, 2021). "As a matter of fact, both CDC20 and BIRC5 were found to be co-expressed in lung adenocarcinoma, endometrial cancer, renal cell carcinoma, and thyroid carcinoma." (PMID 32043523, 2020). "Our results suggest that the miR-195/BIRC5 axis is a potential target for treatment of lung adenocarcinoma specifically, and NSCLC in general." (PMID 29416000, 2018). "Notably, in lung adenocarcinoma (LUAD), BIRC5 overexpression is strongly associated with poor prognosis across multiple clinical features." (PMID 39703228, 2024). "The inhibition of BIRC5 could therefore serve as a potential therapeutic strategy to limit tumor progression and improve patient outcomes in lung adenocarcinoma." (PMID 39703228, 2024). "It has been suggested that TUBB might be involved in mediating metastasis in lung adenocarcinoma, possibly through the interaction with miR-195 that targets BIRC5; however the exact mechanism remains to be unclear." (PMID 36140469, 2022). "It has been shown that LINC00857 enhances BIRC5-dependent radio-sensitivity of cancer cells, regulates apoptosis and glycolysis, and is identified as one of the prognostic markers for the early stage lung adenocarcinoma." (PMID 36105077, 2022). "BIRC5 is also reported to be one of the prognostic markers for lung adenocarcinoma." (PMID 34372869, 2021). "Human lung adenocarcinoma A549 cell line was transfected with LV5-Homo BIRC5." (PMID 32883260, 2020). "This study was aimed at investigating the prognostic significance of Baculoviral IAP repeat containing 5 (BIRC5) in lung adenocarcinoma (LAD) lacking EGFR, KRAS, and ALK mutations (triple-negative (TN) adenocarcinomas)." (PMID 31093306, 2019). "Importantly, miR-195 and BIRC5 expression are significantly associated with lung adenocarcinoma patient survival, but not squamous cell carcinoma patient survival, suggesting that the miR-195/survivin axis might be a more important prognostic marker and therapeutic target in lung adenocarcinoma." (PMID 29416000, 2018).